Y_RNA (Y RNA )
Gene: Miscellaneous RNA gene on chromosome 11 (75,835,215 to 75,835,323, reverse strand). Ensembl gene ENSG00000200256.
Homologues: Orthologues: chimpanzee Y_RNA (99% identical). Paralogues in human: RNY1P5 (85% identical), Y_RNA (84% identical), Y_RNA (83% identical), Y_RNA (82% identical), Y_RNA (81% identical), Y_RNA (80% identical), RNY1 (79% identical), RNY1P1 (79% identical), Y_RNA (79% identical), RNY1P14 (78% identical), Y_RNA (78% identical), RNY1P2 (77% identical), and 92 more.